AKT3 (AKT serine/threonine kinase 3)
Diseases named in the same sentence as AKT3 in open-access papers (continued):
Sharing a sentence is not in itself a finding about the gene and the disease.
angiosarcoma (2 papers, 2021 to 2024). A malignant tumor arising from the endothelial cells of the blood vessels. "Cytogenetically, the expression of FLT1 and AKT3 in the angiosarcomas patients was up-regulated." (PMID 33509230, 2021).
autism (2 papers, 2021 to 2022). Persistent deficits in social interaction and communication and interaction as well as a markedly restricted repertoire of activity and interest as well as repetitive patterns of behavior. "Further, our cell-based data is consistent with the recent addition of PPP2R5D to the list of autism susceptibility genes related to AKT3, PIK3CA, PTEN, TSC1/2, and mTOR." (PMID 33482199, 2021).
cognitive decline (2 papers, 2022 to 2025). "Causative or predisposing variants have been linked to altered PI3K signaling with increased risk of cognitive decline in PIK3CD, AKT3, and TSC1/2." (PMID 40806341, 2025). "In conclusion, the miR‐15a/16‐1‐IL/10RA/AKT3 axis plays a critical role in regulating vascular brain damage and cognitive decline after VCID." (PMID 35403823, 2022). "Our data indicate that miR‐15a/16‐1 regulates vascular brain damage and cognitive decline in VCID brains via translational inhibition of its downstream target gene, AKT3." (PMID 35403823, 2022). "To elucidate the underlying regulatory mechanisms of miR‐15a/16‐1 in the regulation of vascular brain damage and cognitive decline in VCID brains, we conducted bioinformatics analysis of mouse miR‐15a/16‐1 target genes that are related to inflammation, revealing AKT3 as one of the major candidates." (PMID 35403823, 2022).
COVID-19 (2 papers, 2023). A disease caused by infection with severe acute respiratory syndrome coronavirus 2. "AKT3 is of great interest in COVID-19 research as the PI3K/AKT signaling pathway plays a central role in cell survival." (PMID 37137934, 2023). "The presence of AKT3, as well as its isoform AKT2, in our list of prioritized targets supports the predicted association of the PI3K/AKT signaling pathway with COVID-19 as observed in our analysis of the bulk RNA datasets." (PMID 37137934, 2023).
diabetic nephropathy (2 papers, 2020 to 2022). "The expression of circ‐AKT3 and fibrosis‐associated proteins, including fibronectin, collagen type I and collagen type IV, was assessed via RT‐PCR and Western blot analysis in diabetic nephropathy animal model and mouse mesangial SV40‐MES13 cells." (PMID 32597022, 2020). "Circ‐AKT3 was positively correlated to E‐cadherin expression in db/db diabetic nephropathy mice through Pearson's correlation analysis." (PMID 32597022, 2020). "In the present study, we expected to explore the circ‐AKT3 effect on a diabetic nephropathy mouse model and identify the regulation of circ‐AKT3/miR‐296‐3p/E‐cadherin network in the physiology and pathology of diabetic nephropathy." (PMID 32597022, 2020). "In this study, we investigated the significant function of circ‐AKT3/miR‐296‐3p/E‐cadherin regulatory network on the extracellular matrix accumulation in mesangial cells in diabetic nephropathy." (PMID 32597022, 2020). "The level of circ‐AKT3 was significantly lower in diabetic nephropathy mice model group and mouse mesangial SV40‐MES13 cells treated with high‐concentration (25 mmol/L) glucose." (PMID 32597022, 2020). "In addition, to investigate the potential circ‐AKT3 role on diabetic nephropathy progression, RT‐PCR was performed to compare the relative circ‐AKT3 expression in diabetic nephropathy db/db mice with that of the compared normal db/m mice (n = 6)." (PMID 32597022, 2020). "In this study, we investigate the significant circ‐AKT3/miR‐296‐3p/E‐cadherin axis function on the extracellular matrix of mesangial cells in diabetic nephropathy progression, which provides important insights into the management of the disease, especially in early diagnosis and treatment." (PMID 32597022, 2020). "Also, the relative expression of circ‐AKT3 was decreased in diabetic nephropathy db/db mice model." (PMID 32597022, 2020). "In conclusion, circ‐AKT3 inhibited the extracellular matrix accumulation in diabetic nephropathy mesangial cells through modulating miR‐296‐3p/E‐cadherin signals, which might offer novel potential opportunities for clinical diagnosis targets and therapeutic biomarkers for diabetic nephropathy." (PMID 32597022, 2020). "Our study found that circ‐AKT3 suppressed the extracellular matrix accumulation in diabetic nephropathy mesangial cells via regulating miR‐296‐3p/E‐cadherin signals, which may provide a possible biomarker for the diagnosis and treatment of diabetic nephropathy." (PMID 32597022, 2020). "However, the circ‐AKT3 role of diabetic nephropathy progression is still not well‐documented." (PMID 32597022, 2020).
gastric adenocarcinoma (2 papers, 2023 to 2024). "AKT3 protein levels rise as a result of MALAT-1 and AKT3 competition for miR-181a-5p binding, which eventually aids gastric adenocarcinoma cell proliferation and survival." (PMID 38511067, 2024). "The MALAT-1/miR-181a-5p/AKT3 axis plays a critical role in the promotion of gastric adenocarcinoma, as shown by this research." (PMID 38511067, 2024). "Using the AKT antagonist ipatasertib or overexpressing miR-181a-5p had comparable effects to MALAT-1 knockdown, highlighting the significance of the MALAT-1/miR-181a-5p/AKT3 axis in the development of gastric adenocarcinoma." (PMID 38511067, 2024). "Metastasis-associated lung adenocarcinoma transcript 1 (MALAT1), also known as non-coding nuclear-enriched abundant transcript 2 (NEAT2), promotes gastric adenocarcinoma through the MALAT1/miR-181a-5p/AKT3 axis." (PMID 37998329, 2023). "Furthermore, the miR-181a-5p/AKT3 axis plays important roles in gastric adenocarcinoma, TNBC, and UM." (PMID 37998329, 2023).
gastrointestinal stromal tumor (2 papers, 2011 to 2015). "Several patients had multiple aberrations; a patient with wild-type gastrointestinal stromal tumor harbored five alterations (MDM4, MCL1, KIT, AKT3, and PDGRFA)." (PMID 26328274, 2015).
hyperglycaemia (2 papers, 2025). "Akt2 knockout mice exhibited a diabetic phenotype accompanied by hyperglycemia, impaired INS action, reduced circulating leptin, and mild growth retardation, whereas Akt2 and Akt3 double knockout mice exhibited hyperinsulinemia, hyperglycemia, and reduced brain volume." (PMID 39984861, 2025).
hypoglycaemia (2 papers, 2017 to 2023). "This case showed that patients with bi-allelic PTEN mutations can present with other PI3K-AKT-mTOR pathway-related features, including the recurrent respiratory infections observed in patients with PIK3CD mutations and hypoglycaemia observed in patients with AKT2 or AKT3 mutations." (PMID 29296277, 2017).
intrahepatic cholangiocarcinoma (2 papers, 2021 to 2022). A carcinoma that arises from the intrahepatic bile duct epithelium in any site of the intrahepatic biliary tree. "In intrahepatic cholangiocarcinoma, m2 polarized tumor-associated macrophages promote epithelial-mesenchymal transformation by activating AKT3/PRAS40 signaling pathway." (PMID 34983559, 2022). "Moreover, M2-polarized tumor-associated macrophages is demonstrated to be capable of promoting EMT through AKT3 activation in intrahepatic cholangiocarcinoma." (PMID 33653348, 2021).
kidney cancer (2 papers, 2014 to 2025). Primary or metastatic malignant neoplasm involving the kidney. "In the A-498 kidney cancer cell, a positive correlation (p < 0.05) was observed between miR-181a expression and the mRNA expression of FOXO1, FOXO3, PDCD4, AKT3, JNK1 and LAMTOR3." (PMID 41462911, 2025).
liver fibrosis (2 papers, 2015 to 2024). "Among the miRNAs predicted to target genes, we revealed for the first time that PIK3R1 and AKT3 act as critical effectors of miR-29b in liver fibrosis." (PMID 25356754, 2015). "In particular, we demonstrated by a variety of in vitro and in vivo approaches that phosphoinositide-3-kinase regulatory subunit 1 (PIK3R1) and protein kinase B (AKT3) are direct targets of miR-29b in HSCs responsible for signaling onset of HSCs activation and liver fibrosis." (PMID 25356754, 2015). "In contrast, CCl4-treated mice supplemented with miR-29b showed significant reduced expression of PIK3R1, total AKT3 and p-AKT, which paralleled the improvement in histological severity of liver fibrosis." (PMID 25356754, 2015). "To characterize the effect of PIK3R1 or AKT3 on liver fibrosis, we knockdown PIK3R1 or AKT3 expression in LX1 cells by siRNA transfection." (PMID 25356754, 2015). "Furthermore, studies highlighting the mechanisms by which SREBP1c regulates hepatic stellate cells and liver fibrosis have revealed that the overexpression of SREBP1c inhibits liver fibrosis in mice by reducing TGF-β levels and signaling through SMAD3 and AKT1, AKT2, and AKT3." (PMID 38256181, 2024).
lymph node metastases (2 papers, 2008 to 2025). "In addition, the late TNM stage, large tumor size and lymph node metastasis were associated with an increased expression of AKT3 and FGFR2." (PMID 40057671, 2025). "We identified two lymph node metastases (from a single patient) that had the AKT3 E17K mutation." (PMID 18813315, 2008).
lymphoma (2 papers, 2018 to 2019). A malignant (clonal) proliferation of B- lymphocytes or T- lymphocytes which involves the lymph nodes, bone marrow and/or extranodal sites. "The PI3K signaling pathway is usually activated in lymphoma, and inactivation of this pathway impairs DNA repair following radiation, then, we found that levels of both AKT2 and AKT3 were reduced in all miR-150 transductants." (PMID 29386059, 2018). "These include AKT3, ERCC5 and maybe ARID1A as general MMR-D targets, but also POLE as lymphoma-specific neoantigen." (PMID 31581674, 2019).
ovarian endometriosis (2 papers, 2023 to 2025). A non-neoplastic disorder characterized by the growth of endometrial tissue in the ovaries. "miR‐424‐5p attenuated the CDKN2B‐AS1 effect on cell proliferation, invasion, and AKT3 expression in an ovarian endometriosis model." (PMID 36525280, 2023). "In ovarian endometriosis, it has been shown that CDKN2B antisense RNA 1 (CDKN2B-AS1) regulates AKT serine/threonine kinase 3 (AKT3) expression by sponging miR- 424-5p." (PMID 40792071, 2025).
ovarian tumor (2 papers, 2016 to 2019). "The effect of AKT3 on the ovarian tumor cells consists in a moderate acceleration of tumor progression and metastasis." (PMID 31752925, 2019).
psoriasis (2 papers, 2024 to 2025). An autoimmune condition characterized by red, well-delineated plaques with silvery scales that are usually on the extensor surfaces and scalp. "LncRNA AGAP2-AS1 is up-regulated in the lesion area of psoriasis patients and regulates keratinocytes via the miR-424-5p/AKT3 axis." (PMID 38848163, 2024).
skin cancer (2 papers, 2008 to 2022).
T cell lymphoma (2 papers, 2018 to 2023). "MiR-150 increases the sensitivity of NK/T cell lymphoma to ionizing radiation through direct targeting AKT3, but it is significantly diminished in NK/T cell lymphoma tissues and cell lines." (PMID 37998329, 2023). "Furthermore, luciferase reporter assays in NK/T cell lymphoma cells transfected with the AKT2 or AKT3 three prime untranslated region reporter constructs established AKT2 and AKT3 as direct targets of miR-150." (PMID 29386059, 2018).
thymoma (2 papers, 2021 to 2022). A neoplasm arising from the epithelial cells of the thymus. "Significant enrichment of mutated genes of the RAS and PI3K-Akt signalling pathways was reported in thymomas (AKT3, ALK, CSF1R, FGFR4, KRAS, NRAS, HRAS, PIK3CA), and their role in thymoma development was suggested." (PMID 35884448, 2022).
uveal melanoma (2 papers, 2020 to 2022). A melanoma derived from melanocytes of the uveal tract. "In uveal melanoma, miR-224-5p expressed lower compared to normal tissue and was involved in the proliferation, invasion, and migration via regulating the expression of PIK3R3 and AKT3." (PMID 36212129, 2022).
acral melanomas (1 paper, 2024). "Activating E17K missense mutations in the AKT3 gene have been described in acral melanoma, breast, ovarian, and colorectal cancer." (PMID 39614261, 2024). "However, overexpression of AKT3 has been reported in about 60% of hepatitis C virus-associated hepatocellular carcinomas, 10% of acral melanomas, and ~ 20% of ovarian cancers." (PMID 39614261, 2024).
acute graft versus host disease (1 paper, 2022). A syndrome of immunologically mediated tissue damage that may occur following an allogeneic transplant, usually affecting the skin, liver, and GI tract. "MiR-150, which also showed downregulated expression in patients with ASO, has been reported to negatively regulate the function of CD4+ T cells through the AKT3/Bim signaling pathway in acute graft-versus-host disease." (PMID 35428200, 2022).
acute promyelocytic leukemia (1 paper, 2024). An aggressive form of acute myeloid leukemia (AML), characterized by arrest of leukocyte differentiation at the promyelocyte stage, due to a specific chromosomal translocation t(15;17) in myeloid cells. "The M3 group, also called “acute promyelocytic leukemia”, and which represents a separate entity characterized by the PML-RARA chromosomal translocation, shows a homogenous pattern of AKT3 expression, and a significant ~ twofold increase in AKT2 expression." (PMID 38528080, 2024).
altitude sickness (1 paper, 2020). Multiple symptoms associated with reduced oxygen at high altitude. "The single-nucleotide polymorphism of AKT3 (rs4590656) was found to be associated with three physiological parameters (hemoglobin, hematocrit, and red blood cell count) in people with chronic altitude sickness, indicating a strong association of this gene with angiogenesis." (PMID 32802554, 2020).
anaplastic astrocytoma (1 paper, 2019). "Additionally, AKT3-174aa expression enhanced the GBM cell sensitivity to radiation while AKT3-174aa knockdown strengthened the insensitivity of anaplastic astrocytoma cells to IR, supporting the tumor-suppressive role of AKT3-174aa." (PMID 31470874, 2019).
anaplastic glioma (1 paper, 2019). "The stable knockdown of circ-AKT3 in SW1783 cells and in Hs683 anaplastic glioma cells only reduced AKT3-174aa expression, instead of reducing that of AKT1, AKT2 and AKT3." (PMID 31470874, 2019).
B-cell CLL (1 paper, 2016). "Similarly, activation of serine/threonine-protein kinases (Akt2 and Akt3) in combination with B-cell CLL/lymphoma (Bcl2), collagen (COL4A1), Src transforming protein (SHC1) lead to the activation of focal adhesion pathway." (PMID 27367858, 2016).
benign prostatic hyperplasia (1 paper, 2015). A non-cancerous nodular enlargement of the prostate gland. "To determine the gene expression level of AKT3 in normal and cancerous prostate tissues, we assayed AKT3 mRNA level in 24 normal prostate tissue, 11 benign prostatic hyperplasia (BPH), and 99 primary tumors from TissueScan Prostate Tissue qPCR Array using quantitative real time-PCR." (PMID 26318033, 2015).
breast invasive carcinoma (1 paper, 2023). "Results from the survival analysis showed that the up-regulated genes AKT3 and VDAC1 and the down-regulated genes ADCYAP1R1, GFAP, and C4A were found to be significantly associated with the overall survival of the patients with breast invasive carcinoma." (PMID 37834358, 2023). "We found that the FTD DEGs, AKT3, UBE2N, VDAC1, ADCYAP1R1, C4A, and GFAP showed significant comorbidity in breast invasive carcinoma patients at a p-value < 0.05." (PMID 37834358, 2023).
Cerebral ischemia (1 paper, 2022). Restriction of arterial blood supply to the brain associated with insufficient oxygenation to support the metabolic requirements of the tissue. "Based on these data, we hypothesized that EA treatment at the GV20 and GV24 acupoints could ameliorate cerebral ischemia/reperfusion injury partially by reducing Pten expression and regulating the Pten/Akt3 pathway." (PMID 36062010, 2022).
chordoma (1 paper, 2020). Chordomas are rare malignant tumors arising from embryonic remnants of the notochord in axial skeleton. "Chordoma with serious dural penetration highly expressed EGF and AKT3 and show evidence of EGFR activation suggesting that RTK inhibitors may be useful for the treatment of dural invasion in chordoma." (PMID 32533822, 2020). "We observed that EGFR (fold change: 2.652), MET (fold change: 4.676), AKT3 (fold change: 3.703) and EGF (fold change: 11.094) which is a ligand of EGFR, were down regulated in chordomas without dural penetration." (PMID 32533822, 2020).
chronic hepatitis b (1 paper, 2023). "This study showed that rs225014 (DIO2), rs532446 (GADD45A), rs12031994 (AKT3), rs11119982 (ATF3), rs10865710 (PPARG) are associated with the increased risk of liver disease progression in chronic hepatitis b carriers." (PMID 37059745, 2023). "As a result, our study demonstrated that rs225014 (DIO2), rs532446 (GADD45A), rs12031994 (AKT3), rs11119982 (ATF3), rs10865710 (PPARG) might contribute to the increased risk of liver disease progression in chronic hepatitis b carriers." (PMID 37059745, 2023).
chronic obstructive pulmonary disease (1 paper, 2023). A chronic and progressive lung disorder characterized by the loss of elasticity of the bronchial tree and the air sacs, destruction of the air sacs wall, thickening of the bronchial wall, and mucous accumulation in the bronchial tree. "XFPC may regulate autophagy by down-regulating the expression of CSF1, MAPK9, MAP3K7, and AKT3, thus achieving the purpose of treating chronic obstructive pulmonary disease." (PMID 37274101, 2023).
congenital heart disease (1 paper, 2019). A heart disease that is present at birth. "Among these genes, AKT1, PDPK1, CDC42, AKT3, and PIK3CA have concrete evidences shown in relation with congenital heart disease; even two of them (AKT1, CDC42) have explicit association with VSD." (PMID 31440271, 2019).
congenital hypothyroidism (1 paper, 2022). A thyroid hormone deficiency present from birth. "We report a patient with a de novo germline AKT3 variant, NM_005465.7:c.233A > G, p.(Gln78Arg), who presented with congenital hypothyroidism in addition to typical AKT3-related brain disorders." (PMID 35665751, 2022).
dementia (1 paper, 2022). Loss of intellectual abilities interfering with an individual's social and occupational functions. "Taken together, we concluded that miR-520f acts as a transcriptional inhibitor of AKT3, and AKT3 reduction will cause the neuropathologic processes of dementia." (PMID 35528544, 2022).
developmental delays (1 paper, 2017). "While developmental delays were observed in all patients, patients with AKT3 or PIK3R2 mutations had no meaningful words and had a more severe disease phenotype than those with PTEN mutations." (PMID 28086757, 2017).
diabetic retinopathy (1 paper, 2023). "The serine/threonine kinase AKT3 binds to D3-PIPs and GWAS study has identified two AKT3 SNP-risk alleles associated with diabetic retinopathy." (PMID 37007713, 2023).
dilated cardiomyopathy (1 paper, 2023). Cardiomyopathy which is characterized by dilation and contractile dysfunction of the left and right ventricles. "AKT3 is significantly upregulated in the hearts of patients with dilated cardiomyopathy, and AKT3 activation protects the heart from injury; however, persistent activation can cause the heart to dilate or hypertrophy." (PMID 37649075, 2023).
endometrial adenocarcinoma (1 paper, 2023). "The oncogenic lncRNA CDKN2B-AS1 has been observed in Ishikawa endometrial adenocarcinoma cells and found to promote cellular proliferation and invasion by sponging miR-424-5p, thus upregulating the expression of AKT3." (PMID 37998329, 2023).